RIPK3 (receptor interacting serine/threonine kinase 3)
Diseases named in the same sentence as RIPK3 in open-access papers (continued):
Sharing a sentence is not in itself a finding about the gene and the disease.
multiple myeloma (4 papers, 2018 to 2025). "We analysed six single-nucleotide polymorphisms in a population of patients with multiple myeloma (n = 205) and healthy volunteers (n = 100): RIPK1 rs2272990, RIPK1 rs9391981, RIPK3 rs724165, RIPK3rs3212243, MAPKAPK2, rs45514798 and MAPKAPK2 rs4073250." (PMID 40508046, 2025). "Here, we demonstrate that omega-3 polyunsaturated fatty acids DHA/EPA and the proteasome inhibitor bortezomib induce necroptosis in human multiple myeloma (MM) cells in a RIPK3 independent manner." (PMID 35965541, 2022). "In the present study, we showed that SNPs located in genes encoding RIPK1, RIPK3 and MAPKAPK2 may be associated with the clinical parameters of multiple myeloma." (PMID 40508046, 2025). "We hypothesise that SNPs located in RIPK1, RIPK3 and MAPKAPK2 could be associated with multiple myeloma survival, treatment outcome and clinical parameters." (PMID 40508046, 2025). "Taken together, the present study suggests a novel role and regulatory mechanisms of necroptosis in multiple myeloma, and may provide a new molecular target (avenue) for therapeutic intervention of certain human cancers with eliminated RIPK3 function." (PMID 35965541, 2022). "The associations we observed between polymorphisms in RIPK1, RIPK3, and MAPKAPK2 genes and patient survival and treatment response reflect deeper biological relationships between genetic variants of necroptosis pathways and the pathophysiology of multiple myeloma." (PMID 40508046, 2025). "Pharmacological inhibition of RIPK1 (Necrostatin-1 (Nec-1)) and RIPK3 (GSK-872) (data not shown) failed to protect myeloma cells from Ad[CE1A]-induced cell death." (PMID 40247106, 2025). "Proteasome inhibitor-sensitive multiple myeloma cell lines die in response to Cf by apoptosis in combination with serine protease-dependent death, without any contribution of RIPK3-dependent necroptosis." (PMID 29497034, 2018). "In the present study, we show that cell death triggers such as DHA, EPA and bortezomib may induce necroptosis in multiple myeloma cells independent of RIPK3." (PMID 35965541, 2022).
myeloid leukaemia (4 papers, 2021 to 2024). "RIPK3‐mediated necrosis has been shown to suppress myeloid leukaemia development specifically by mediating the necrosis of myeloid leukaemia cells." (PMID 38594879, 2024). "And a key role for receptor-interacting serine/threonine-protein kinase 3 (RIPK3) in preventing hematopoietic malignancies is through specific mediation of necroptosis in myeloid leukaemia cells." (PMID 37600653, 2023). "As RIPK3 functions as a powerful tumor suppressor in myeloid leukemia, we set out to investigate the contribution of its downstream partner MLKL to leukemogenesis." (PMID 34079078, 2021).
Obesity (4 papers, 2016 to 2025). Accumulation of substantial excess body fat. "Our findings on the association between RIPK3 overexpression and obesity and metabolic serum parameters in humans clearly indicated that RIPK3 has a similar function in the WAT of obese humans and mice." (PMID 27323669, 2016). "Based on the differing obesity and inflammatory phenotypes observed in RIPK3- versus MLKL-deficient mice, we questioned whether MLKL requires RIPK3 activity to alter lipid metabolism in the liver of HFD-fed mice." (PMID 39532538, 2025). "Together, these data indicate that RIPK3 contributes to obesity-induced metabolic dysfunction, and this is likely, in part, through activation of caspase-8 signaling in myeloid cells." (PMID 39532538, 2025). "This aligns with the previous report showing that RIPK3 acts as an inhibitor of apoptosis in adipocytes during obesity." (PMID 40961178, 2025). "Although the role of upstream kinases RIPK1 and RIPK3 in obesity and MAFLD remain debatable, there are numerous reports that MLKL deficiency protects mice from MAFLD." (PMID 39532538, 2025). "In our hands, MLKL acts independently of canonical RIPK3 signaling to drive obesity and metabolic dysfunction." (PMID 39532538, 2025). "In this study, male hRipk3-KI, hMlkl-KI, and control (Ripk3-KI and Mlkl-KI) mice were fed a WD to induce obesity starting at 2 months of age and compared to mice fed a standard laboratory chow diet (CD)." (PMID 39514172, 2024). "Our results show that obesity triggers RIPK3 overexpression in the WAT of mice and humans, where it dampens adipocyte apoptosis and inflammation, thereby preventing impaired insulin signalling as the basis of glucose intolerance." (PMID 27323669, 2016). "We next examined the effect of the RIPK3 substrate MLKL on the development of obesity and MAFLD." (PMID 39532538, 2025). "As hypothesized, this analysis revealed high expression of RIPK3 in WT mice, suggesting that, next to apoptosis, obesity triggers activation of RIPK3-dependent signalling in adipocytes." (PMID 27323669, 2016). "We finally assessed whether RIPK3 expression is also altered in the visceral fat tissue (visWAT) of human patients with obesity and T2D." (PMID 27323669, 2016). "Moreover, RIPK3 on 6 months of HFD was upregulated in inguinal WAT (iWAT), but less pronounced than in epiWAT, suggesting that RIPK3 upregulation in obesity occurs in a compartment-specific manner." (PMID 27323669, 2016). "As RIPK3 can regulate the death- and inflammation-inducing activity of both caspase-8 and MLKL in disease-causing macrophages, direct comparisons of mutant animals in the same obesity and MAFLD model are required to define their pathological roles and divergent activities." (PMID 39532538, 2025). "Here, we directly contrast the contribution of RIPK3, along with caspase-8 in myeloid cells, and MLKL signaling in obesity and MAFLD development." (PMID 39532538, 2025). "In contrast, MLKL, divergent to RIPK3, contributes to both obesity and MAFLD in a manner largely independent of inflammation." (PMID 39532538, 2025). "In comparison, MLKL appears to drive obesity with aging to promote MAFLD development in a manner independent of canonical RIPK3 signaling." (PMID 39532538, 2025). "How MLKL deficiency protects mice from obesity is unclear, but one recent study proposed that MLKL, and not RIPK3, drives white adipose tissue differentiation." (PMID 39532538, 2025). "We therefore examined whether RIPK3 and caspase-8 contribute to pathological inflammatory changes in HFD-induced obesity." (PMID 39532538, 2025). "RIPK3 showed a similar upregulation of RIPK3 in epiWAT on conventional HFD feeding, as seen in CD-HFD-fed mice, suggesting that, independent of choline deficiency, obesity represents a general stimulator for RIPK3 overexpression in epiWAT." (PMID 27323669, 2016).
Obesity (continued). "This study shows how necroptotic effector MLKL can induce obesity and perturb lipid metabolism to drive MAFLD progression, independent of RIPK3 that regulates inflammatory events." (PMID 39532538, 2025). "More importantly, we delineate a noncanonical, RIPK3-independent role for MLKL in lipid metabolism and the development of obesity and MAFLD." (PMID 39532538, 2025).
Parkinson disease (4 papers, 2024 to 2025). A progressive degenerative disorder of the central nervous system characterized by loss of dopamine producing neurons in the substantia nigra and the presence of Lewy bodies in the substantia nigra and locus coeruleus. "Here, we used the 1-methyl-4-phenyl-1, 2, 3, 6-tetrahydropyridine model of Parkinson’s disease to show that activation of astrocytic RIPK3 drives dopaminergic cell death and axon damage." (PMID 38713518, 2024). "Astrocytic RIPK3 signaling promotes neurodegeneration in the MPTP model of Parkinson’s disease." (PMID 38713518, 2024).
periodontitis (4 papers, 2019 to 2025). An acute or chronic inflammatory process that affects the tissues that surround and support the teeth. "It is well known that the RIPK3 factor selectively contributes to the necroptosis process,therefore, it seems that RIPK3-mediated necroptosis is associated with chronic periodontitis." (PMID 37266108, 2023). "In conclusion, the strong gene expression of RIPK3 in gingival lesions revealed that necroptosis is substantially associated with chronic periodontitis." (PMID 37266108, 2023). "The RIPK3 selectively contributes to necroptosis, therefore, it seems that RIPK3-mediated necroptosis is involved in chronic periodontitis." (PMID 37266108, 2023). "In the current study, the mean expression rate of the RIPK3 gene in the chronic periodontitis group was considerably higher than the control group." (PMID 37266108, 2023). "On the other hand, the expression of the selectively pivotal signaling factor, RIPK3, for inducing necroptosis, was significantly higher in chronic periodontitis than the control group." (PMID 37266108, 2023). "Furthermore, the same test on RIPK3 expression in patients with chronic periodontitis and the control group, revealed that there was a significant difference between these two groups since the expression of RIPK3 was significantly greater in CP patients compared to the control group (p = 0.024)." (PMID 37266108, 2023). "In addition, decreased RIPK1 and RIPK3 can be observed in the periodontal tissue in the experimental periodontitis model after FVD treatment, further indicating that CDK9 may modulate necroptosis during periodontitis progression." (PMID 31758083, 2019). "Recent trials indicated that RIPK3 and MLKL-mediated necroptotic cell death played a role in the development of periodontitis." (PMID 37266108, 2023). "Our research demonstrated that CDK9 activation regulated the inflammatory gene transcription and RIPK3-mixed lineage kinase domain-like (MLKL)-mediated necroptosis following P. gingivalis invasion and further influenced the progress of periodontitis." (PMID 31758083, 2019). "Furthermore, rank-sum test analysis in this study revealed differential expression of key PANoptosome components such as RIPK3, CASP8, and CASP1, suggesting that periodontitis may involve ZBP1-mediated PANoptosome formation." (PMID 40612110, 2025).
renal failure (4 papers, 2016 to 2025). "However, in the derivation cohort, plasma RIPK3 was also elevated in patients with single kidney failure but the levels were lower than those with single liver failure." (PMID 34921136, 2021). "Our team has been investigating RIPK1/RIPK3 and its role in necrotic apoptosis for years, and our previous study showed that the RIPK1 antagonist Cpd-71 prevents cisplatin-induced renal insufficiency by reducing necroptosis and inflammation." (PMID 40351427, 2025).
retinal degeneration (4 papers, 2015 to 2025). Degeneration of the retina. "Drusen-derived dsRNA also promotes necroptosis of RPE, and contributes to inflammation and retinal degeneration, which can be prevented by RIPK3 deficiency." (PMID 39872161, 2022). "The genetic deletion of Ripk3 was shown to protect photoreceptors in mouse models of retinal degeneration, such as rd10 mice, retinal detachment, and alkylation-induced degeneration." (PMID 40943078, 2025). "These new data support and expand upon previous evidence that RIPK3 contributes to retinal degeneration." (PMID 40943078, 2025). "We also investigated whether a factor involved in the necrosis process, RIPK3, was expressed during the retinal degeneration phase." (PMID 33324144, 2020). "It has been shown that RPE cells undergo necroptosis rather than apoptosis in a mouse model of oxidative stress-induced retinal degeneration, which can be block by RIPK1 inhibitor or silencing of RIPK3." (PMID 39872161, 2022).
Salmonella Infections (4 papers, 2016 to 2024). Infections with bacteria of the genus SALMONELLA. "To investigate the relative importance of pyroptosis, necroptosis, and apoptosis during Salmonella infection, we infected mice and macrophages deficient for diverse combinations of caspases-1, -11, -12, and -8 and receptor interacting serine/threonine kinase 3 (RIPK3)." (PMID 32735843, 2020). "To investigate this, we generated Casp1–/–;Casp8–/–;Ripk3–/– iBMDMs and compared their death kinetics upon Salmonella infection to those of Casp1–/–;Casp11–/–;Casp12–/–;Casp8–/–;Ripk3–/– cells." (PMID 32735843, 2020). "Ripk3-/-Casp8-/- BMDMs showed dramatically reduced IL-6 and IL-12p40 production compared with B6 or Ripk3-/- cells in response to Yersinia and Salmonella infection." (PMID 27737018, 2016). "Only the combined absence of caspases-1, -11, -12, and -8 and RIPK3 completely blocked Salmonella-infection-induced killing of iBMDMs." (PMID 32735843, 2020). "Furthermore, mice with previously known caspase-3/11 deletions were shown to have an impaired ability to control the Salmonella burden, whereas RIPK3 deletion alone did not affect the innate immune response to Salmonella infection." (PMID 38933265, 2024). "Non-invasive S. typhimurium does not naturally induce RIPK3-dependent macrophage death, whereas macrophage necroptosis can only be induced when caspase is inhibited using Z-VAD-FMK, and RIPK3 induction (after caspase inhibition) does not affect host survival after systemic Salmonella infection." (PMID 38933265, 2024).
toxic epidermal necrolysis (4 papers, 2023 to 2026). Toxic epidermal necrolysis (TEN) is an acute and severe skin disease with clinical and histological features characterized by the destruction and detachment of the skin epithelium and mucous membranes. "RIPK3 has been associated with other autoimmune diseases, such as psoriasis, toxic epidermal necrolysis (TEN), RA, osteoarthritis (OA), Crohn’s disease, and pancreatitis." (PMID 38684668, 2024). "Recently, a role for RIPK3 in toxic epidermal necrolysis (TEN) has been described." (PMID 37688617, 2023). "Necroptosis has been implicated in the pathogenesis of Stevens-Johnson syndrome and toxic epidermal necrolysis (SJS/TEN), with prior studies demonstrating tissue-level involvement of receptor-interacting protein kinases RIPK1 and RIPK3." (PMID 42193144, 2026).
type 2 diabetes (4 papers, 2020 to 2022). "In the type 2 diabetes zebrafish model, Ripk3 contributes to islet inflammation by inducing local IL-1β production and recruiting macrophages." (PMID 35220408, 2022). "A number of the genes highlighted in this study present strongly as having a potential role in bone biology, including CPE, FBN2, FLCN and RIPK3, and our results support the growing body of evidence suggesting that the CPE gene may exert pleiotropic effects on type 2 diabetes and osteoporosis." (PMID 32216834, 2020).
ulcerative colitis (4 papers, 2016 to 2022). An inflammatory bowel disease involving the mucosal surface of the large intestine and rectum. "The purpose of this study was to explore the therapeutic effect of pine pollen polysaccharides and sulfated polysaccharides on UC mice and whether they affect ulcerative colitis in mice by regulating cells’ tight junction and regulating the RIPK3 pathway." (PMID 36431783, 2022).
Ureteral obstruction (4 papers, 2019 to 2025). Obstruction of the flow of urine through the ureter. "Unilateral ureteral obstruction (UUO) in the neonatal mouse caused renal structural injury, induced key molecules of the necrosome (RIPK3 and phospho-MLKL) and generated inflammatory cytokines (IL-1α, INF-γ and TNF-α) in the neonatal kidney." (PMID 31819111, 2019).
Yersinia infection (4 papers, 2016 to 2024). "It has been suggested that co-assembly of ASC, NLRP3, RIPK3, caspase-1, and caspase-8 triggers PANoptosis during Yersinia infection." (PMID 39058785, 2024). "Recently, Yersinia infection was found to activate PANoptosis, with infection inducing the formation of a PANoptosome containing RIPK1, RIPK3, caspase-8, ASC, FADD, and NLRP3." (PMID 35563804, 2022). "PANoptosomes have also been identified by immunoprecipitation during Yersinia infection, where RIPK1, RIPK3, caspase-8, FADD, ASC, and NLRP3 can be co-immunoprecipitated." (PMID 35563804, 2022). "RIPK3/MLKL-induced programmed necrosis also activates NLRP3, presumably via potassium efflux, thereby providing another route to caspase-1 engagement during Yersinia infection, even when caspase-8 cannot be activated." (PMID 39058785, 2024). "Another unexpected finding here was that while Casp8DA/DA macrophages did not undergo apoptosis in response to Yersinia infection, they still undergo RIPK3-dependent necrosis, rather than being protected from death." (PMID 27737018, 2016). "RIPK3 makes no detectable contribution to Yersinia-induced cell death, and we do not observe any evidence for RIPK3-mediated necroptosis during Yersinia infection in the presence of functional caspase-8." (PMID 39058785, 2024). "Moreover, neither RIPK3 nor MLKL undergoes phosphorylation in WT cells during Yersinia infection or IKK blockade, suggesting that necroptosis is not activated by Yersinia when caspase-8 is present and functional." (PMID 39058785, 2024).
ZIKV infection (4 papers, 2020 to 2025). "We also found that inhibition of PANoptosis by treatment with pan-caspase inhibitor Z-VAD-FMK and RIPK3 inhibitor GSK872 together or RIG-I inhibitor RIG012 can attenuate placental inflammatory damages caused by ZIKV infection." (PMID 41263557, 2025). "In contrast, viral titers were significantly higher in GSK’872-treated cells compared to untreated cells, further demonstrating that RIPK3-denpendent necroptosis induced by ZIKV infection can be protective against viral replication in human astrocytes." (PMID 33796483, 2021). "Thus activation of RIPK3 can suppress ZIKV infection through various mechanisms depending on cell types in the brain that are infected." (PMID 33796483, 2021). "Significant loss of cell viability was exhibited in the infected cells without RIPK3 inhibition while the GSK’872-pre-treated cells survived the ZIKV infection." (PMID 33796483, 2021). "Interestingly necroptosis was induced upon RIPK3 and this cell death appeared to be RIPK3-dependent because it could be suppressed by an inhibitor of RIPK3, indicating that astrocytes may differ from neurons in RIPK3 signaling after cellular sensing of ZIKV infection." (PMID 33796483, 2021).
anemia (3 papers, 2020 to 2024). A reduction in the number of red blood cells, the amount of hemoglobin, and/or the volume of packed red blood cells. "Notably, although anemia in Abin1Q478H/Q478H mice was ameliorated by Ripk3 deficiency, the Abin1Q478H/Q478HRipk3–/–, Abin1Q478H/Q478HRipk1K45A/K45A, and Abin1Q478H/Q478HMlkl–/– mice still showed severe thrombocytopenia, similar to the Abin1Q478H/Q478H mice." (PMID 38009796, 2024). "Taken together, these results indicate that Ripk3 deletion can partially ameliorate anemia defects in Abin1Q478H/Q478H mice." (PMID 38009796, 2024). "This indicates that the necroptosis‐independent function of RIPK3 is critical for anemia development in Abin1Q478H/Q478H mice." (PMID 38009796, 2024). "Casp8–/–Ripk3–/– double‐knockout mice exhibit higher levels of RBCs and platelets than Casp8–/–Mlkl–/– double‐knockout mice.[34a] Our study revealed that RIPK3 regulates Abin1Q478H/Q478H anemia through necroptosis‐independent mechanisms." (PMID 38009796, 2024). "As expected, anti-IL-6R antibody therapy alleviated anemia and thymus atrophy in Apcmin/+Ripk3-/- mice." (PMID 33996591, 2021). "Accordingly, anemia and thymus atrophy were significantly exacerbated in Apcmin/+Ripk3-/- mice compared to the Apcmin/+ littermate controls." (PMID 33996591, 2021). "Considering that RIPK3 deletion could prevent compensated anemia in glutathione peroxidase 4 (Gpx4)‐deficient mice and BMF in Tak1mutTnfr−/− mice, we investigated whether Abin1Q478H/Q478H drives hematopoiesis defects through an RIPK3‐dependent pathway." (PMID 38009796, 2024). "Given that RIPK3 participates in various necroptosis‐independent signaling pathways, such as apoptosis, senescence, inflammation, and autophagy, we further examined whether its deletion prevents anemia in Abin1Q478H/Q478H mice by blocking RIPK1–RIPK3–MLKL axis‐mediated necroptosis." (PMID 38009796, 2024). "However, RIPK3 only plays a necroptosis‐independent role in anemia, and it does not regulate thrombocytopenia." (PMID 38009796, 2024).